Y_RNA (Y RNA )
Gene: Miscellaneous RNA gene on chromosome 5 (2,184,710 to 2,184,820, forward strand). Ensembl gene ENSG00000201026.
Homologues: Orthologues: chimpanzee Y_RNA (97% identical), macaque Y_RNA (82% identical), mouse Gm26329 (71% identical). Paralogues in human: RNY1P16 (74% identical), Y_RNA (74% identical), RNY1 (71% identical), Y_RNA (71% identical), RNY1P10 (70% identical), RNY1P11 (70% identical), Y_RNA (70% identical), Y_RNA (69% identical), Y_RNA (68% identical), RNY1P5 (68% identical), RNY1P14 (67% identical), RNY1P3 (67% identical), and 84 more.